HSFY1 (heat shock transcription factor Y-linked 1)
Synonyms: HSF2L; HSFY
Gene: Protein-coding gene on chromosome Y (18,546,691 to 18,588,963, forward strand). Ensembl gene ENSG00000172468.
Subcellular location: Nucleus; Cytoplasm
Subcellular location (Human Protein Atlas): Cytosol; Nucleoplasm
Gene Ontology:
Molecular function: protein binding; sequence-specific double-stranded DNA binding; DNA-binding transcription factor activity, RNA polymerase II-specific; RNA polymerase II cis-regulatory region sequence-specific DNA binding; DNA-binding transcription factor activity; sequence-specific DNA binding
Biological process: regulation of transcription by RNA polymerase II; regulation of DNA-templated transcription
Cellular component: cytosol; nucleoplasm; chromatin; cytoplasm; nucleus
Homologues: Orthologues: rat Hsfy2 (45% identical), mouse Hsfy2 (44% identical), Caenorhabditis elegans hsf-1 (15% identical), Drosophila melanogaster Hsf (14% identical). Paralogues in human: HSFY2 (100% identical), HSFX1 (29% identical), HSFX2 (29% identical), HSFX3 (19% identical), HSFX4 (19% identical), HSF1 (18% identical), HSF2 (17% identical), HSF4 (17% identical), HSF5 (16% identical).
Diseases named in the same sentence as HSFY1 in open-access papers:
HSFY1 is named in the same sentence as 5 diseases in open-access papers, as found by Europe PMC text mining. Sharing a sentence is not in itself a finding about the gene and the disease. The quoted sentences say what the papers report.
male infertility (1 paper, 2020). The inability of the male to effect fertilization of an ovum after a specified period of unprotected intercourse. "Some of these genes, including PRY, HSFY1, and DAZ, are strongly linked to male infertility." (PMID 33318309, 2020).
HSFY1 also shares sentences with these, for which no sentence is quoted: Azoospermia (2 papers); infertile (2); cancer (1); oligospermia (1).